HTT (huntingtin)
Diseases named in the same sentence as HTT in open-access papers (continued):
Sharing a sentence is not in itself a finding about the gene and the disease.
Huntington disease (continued). "Huntington's disease (HD) is a hereditary neurodegenerative disease caused by the expansion of a polyglutamine stretch in the huntingtin (HTT) protein and characterized by dysregulated calcium homeostasis." (PMID 24324398, 2013). "Huntington’s disease (HD), for instances, is associated with an expansion in exon 1 of the huntingtin gene, which leads to an aberrant polyglutamine tract in the huntingtin protein." (PMID 23179684, 2013). "In the lone false positive, game players suggested that the HTT gene (“huntingtin”), which is known to be implicated in Huntington's disease, was involved in Alzheimer's disease." (PMID 23951102, 2013). "Huntington’s disease (HD) is caused by the abnormal expansion of the polyglutamine tract in the human Huntingtin protein (polyQ-hHtt)." (PMID 23861941, 2013). "In relation to its role in protein aggregation, huntingtin, a causal gene product of Huntington disease, is known to be phosphorylated by Akt under the influence of the IGF-PI3K pathway." (PMID 24358196, 2013). "Changes in cortical Bdnf expression levels, and/or impairment in brain-derived neurotrophic factor anterograde transport induced by mutant huntingtin (mHdh) are believed to cause striatopallidal neuron vulnerability in early-stage Huntington’s disease." (PMID 23774276, 2013). "Huntington’s disease (HD) is an autosomal dominant neurodegenerative disorder caused by the expansion of a CAG trinucleotide repeat in the HTT gene encoding huntingtin." (PMID 24278347, 2013). "Huntington’s disease (HD) is a monogenic disorder caused by an aberrant expansion of CAG repeats in the huntingtin gene (HTT)." (PMID 24274906, 2013). "Huntingtin (Htt), a ubiquitously expressed protein, when mutated, forms toxic intracellular aggregates - the hallmark of Huntington’s disease (HD)." (PMID 24116161, 2013). "Huntington disease (HD) is a neurodegenerative disease caused by the pathological elongation of the CAG repeats in exon 1 of the huntingtin protein gene." (PMID 24330821, 2013). "Huntington's disease (HD) is a neurodegenerative disorder caused by abnormal polyglutamine expansion in the amino-terminal end of the huntingtin protein (Htt) and characterized by progressive striatal and cortical pathology." (PMID 23691206, 2013). "Huntington's disease (HD) is a progressive fatal neurodegenerative disease caused by CAG repeat expansions in the huntingtin (HTT) gene." (PMID 24086450, 2013). "The bulk of interest in the huntingtin protein has centred on the fact that, when mutated, huntingtin causes Huntington's disease (HD), a devastating neurodegenerative disorder." (PMID 23300147, 2013). "Amyloid-like inclusions have been associated with Huntington's disease (HD), which is caused by expanded polyglutamine repeats in the Huntingtin protein." (PMID 24367279, 2013). "Intracellular accumulation of polyglutamine (polyQ)-expanded Huntingtin (Htt) protein is a hallmark of Huntington’s disease (HD)." (PMID 23762270, 2013). "Huntington’s disease (HD) is an autosomal dominant disorder caused by a tandem repeat expansion encoding an expanded tract of glutamines in the huntingtin protein." (PMID 23847583, 2013). "Huntington’s Disease (HD) is a progressive neurodegenerative disorder caused by an expansion in the polyglutamine (polyQ) region of the Huntingtin (HTT) gene." (PMID 23957861, 2013). "Huntington’s disease (HD) is a progressive neurodegenerative disorder caused by a polyglutamine-encoding CAG expansion in the huntingtin gene." (PMID 24146952, 2013). "Huntington’s disease (HD) is a fatal neurodegenerative disorder caused by the amplification of a polyglutamine stretch at the N-terminus of the huntingtin (htt) protein." (PMID 24376631, 2013).
Huntington disease (continued). "In this paper, we demonstrated that miRNAs regulate the expression of the HTT gene, whose mutation leads to Huntington’s disease (HD), a hereditary degenerative disorder." (PMID 23965969, 2013). "Huntington’s disease (HD) is a devastating dominantly inherited neurodegenerative disorder caused by an abnormal polyglutamine expansion in the N-terminal part of the huntingtin (HTT) protein." (PMID 23555909, 2013). "Huntington's disease (HD) is an incurable neurodegenerative disorder caused by a CAG repeat expansion in exon 1 of the Huntingtin (HTT) gene." (PMID 23576953, 2013). "Huntington’s disease (HD) is an autosomal dominant neurodegenerative disease caused by trinucleotide repeat expansions in the Huntingtin gene (Htt)." (PMID 24312010, 2013). "Huntington’s Disease (HD) is a genetic neurodegenerative disease caused by a CAG expansion in the gene encoding Huntingtin (Htt)." (PMID 24167500, 2013). "Huntington's disease (HD) is an autosomal dominantly inherited disorder caused by the expansion of CAG repeats in the Huntingtin (HTT) gene." (PMID 22383888, 2012). "Huntington's disease (HD) is an autosomal dominant inherited disease caused by expansion of a CAG triplet-repeat within the first exon of the Huntingtin (HTT) gene." (PMID 22363539, 2012). "Huntington's disease (HD) is an autosomal dominant neurodegenerative disorder caused by an elongated, unstable, polyglutamine repeat near the N terminus of the huntingtin gene." (PMID 22475209, 2012). "In terms of their relationships to diseases, the SH3 domains of CIP4 bind to the huntingtin protein, which is mutated in patients with Huntington disease." (PMID 24957964, 2012). "The hallmark of Huntington's disease, the accumulation of mutant huntingtin protein within neurons, is affected by the inefficient palmitoylation of huntingtin." (PMID 23119149, 2012). "Huntington Disease (HD) is caused by an abnormal expansion of polyQ tract in the protein named huntingtin (Htt)." (PMID 23071649, 2012). "For example, more than 36 polyQ repeats in mutant huntingtin (mtHtt) causes aggregation of the protein in the cytoplasm of affected cells causing Huntington disease." (PMID 23148417, 2012). "Huntington's disease is caused by an expansion of exonic CAG triplet repeats in the gene encoding the Huntingtin protein (Htt) that appear to be toxic." (PMID 22615071, 2012). "Impairments in mitochondria and transcription are important factors in the pathogenesis of Huntington disease (HD), a neurodegenerative disease caused by a polyglutamine expansion in the huntingtin protein." (PMID 22276192, 2012). "One well known example is Huntington's disease (HD), which is caused by an expansion of the poly-Q stretch, located within the N-terminal stretch of the essential protein called huntingtin (Htt)." (PMID 22536159, 2012). "Huntington's disease is a progressive neurodegenerative disease, caused by a polyglutamine expansion in the huntingtin protein." (PMID 23050151, 2012). "Huntington’s disease is an incurable neurodegenerative disorder caused by expansion of a CAG trinucleotide repeat within one allele of the huntingtin (HTT) gene." (PMID 23042244, 2012). "Huntington’s disease (HD) is a neurodegenerative disorder caused by the inheritance of one mutant copy of the huntingtin gene." (PMID 22815947, 2012). "Huntington’s disease is an autosomal dominant neurodegenerative disease caused by CAG trinucleotide repeat expansion in huntingtin, which encodes Huntingtin (Htt)." (PMID 23056009, 2012). "Huntington’s disease (HD) is a fatal neurodegenerative disorder caused by a CAG repeat expansion in the huntingtin (HTT) gene." (PMID 23251447, 2012). "Huntington’s disease (HD) is a fatal progressive neurodegenerative disorder caused by the expansion of the polyglutamine repeat region in the huntingtin gene." (PMID 22741533, 2012).
Huntington disease (continued). "Huntington’s disease (HD) is an autosomal dominant neurodegenerative disease that is caused by the expansion of a polyglutamine (polyQ) stretch within Huntingtin (htt), the protein product of the HD gene." (PMID 22892315, 2012). "Since the A2A-R was implicated as a therapeutic target in treating Huntington’s disease (HD), a cellular model of HD was applied by transfecting mutant huntingtin in PC12 cells." (PMID 22719969, 2012). "Huntington's disease (HD) is a neurodegenerative disorder caused by an abnormal CAG expansion in the Huntingtin gene (HTT), resulting in an expanded polyglutamine track in the HTT protein." (PMID 22383888, 2012). "Huntington's disease (HD) is a neurodegenerative disorder caused by a tandem repeat expansion encoding a polyglutamine tract in the huntingtin protein." (PMID 22830053, 2012). "Huntington's disease (HD) is caused by expanded CAG repeats encoding a polyglutamine tract in the huntingtin (HTT) protein." (PMID 23029535, 2012). "Huntington disease (HD) is largely a hereditary neurodegenerative disorder associated with expansion of the polyglutamine region in the gene encoding the protein huntingtin (Htt)." (PMID 22523492, 2012). "Huntington's disease (HD) is an inherited disorder caused by mutation of the gene that encodes the huntingtin protein." (PMID 23209424, 2012). "Genetic evidence in humans and mouse models of Huntington's disease suggests that the disease mutation confers a deleterious gain-of-function on huntingtin that acts through the deregulation of some aspect of the protein's normal function(s)." (PMID 21552328, 2011). "Huntington’s disease (HD) is an inherited disorder caused by expansion of a polyglutamine repeat within exon 1 of the huntingtin gene on chromosome 4 (Huntington’s Disease Collaborative Research Group)." (PMID 21841917, 2011). "Proteolytic processing of mutant huntingtin (mHtt), the protein that causes Huntington's disease (HD), is critical for mHtt toxicity and disease progression." (PMID 21304966, 2011). "Huntington's disease (HD) is a neurodegenerative disorder caused by a dominantly heritable expansion of a trinucleotide CAG repeat in the huntingtin (htt) gene, and characterized by the preferential neurodegeneration of striatal medium-sized spiny neurons." (PMID 22041125, 2011). "Huntington's disease (HD) is caused by the expansion of N-terminal polymorphic poly Q stretch of the protein huntingtin (HTT)." (PMID 21887328, 2011). "We next asked if our deletion strains also affect the [PIN+] dependent aggregation of the polyglutamine (polyQ) expanded repeat found in the mutant huntingtin protein associated with Huntington's disease." (PMID 21625618, 2011). "Huntington's disease (HD) is an autosomal dominant neurodegenerative disorder caused by expansion of CAG repeats in exon 1 of the huntingtin gene." (PMID 21760962, 2011). "Of potentially greatest interest was the novel finding of a high degree of connectivity between the DISC1 scaffold protein, linked to psychiatric illness, and huntingtin, the protein which is mutated in Huntington's disease." (PMID 21298101, 2011). "Huntington's disease is caused by a polyglutamine (polyQ) tract expansion near the amino-terminus of the protein huntingtin." (PMID 21858230, 2011). "While Huntington's Disease is known to be caused by a CAG triplet repeat in the gene Huntingtin, the effect of CAG repeats on brain function below disease threshold has not been studied." (PMID 22008211, 2011). "Abnormalities in mitochondrial function and epigenetic regulation are thought to be instrumental in Huntington's disease (HD), a fatal genetic disorder caused by an expanded polyglutamine track in the protein huntingtin." (PMID 21931779, 2011). "Huntington's disease is caused by aggregation of mutant huntingtin (mHtt) protein containing more than a 36 polyQ repeat." (PMID 21631942, 2011).
Huntington disease (continued). "Huntington’s disease (HD) is a progressive neurodegenerative disease caused by a CAG expansion of the huntingtin gene." (PMID 21479110, 2011). "Huntington's disease (HD) is a progressive neurodegenerative disorder caused by a polyglutamine expansion in the Huntingtin protein which results in the selective degeneration of striatal medium spiny neurons (MSNs)." (PMID 22118545, 2011). "Huntington's disease (HD) is caused by the expansion of a polyglutamine (polyQ) tract in the first exon (HDx-1) of the large protein, huntingtin (Htt)." (PMID 21304966, 2011). "Huntington disease (HD) is caused by a polyglutamine expansion of more than 35 units in the huntingtin protein." (PMID 21211002, 2011). "Huntington's disease (HD) is a neurodegenerative disease caused by a CAG trinucleotide expansion in the Huntingtin (Htt) gene." (PMID 21713039, 2011). "Huntington's disease (HD) is a fatal autosomal dominant neurodegenerative disorder caused by a trinucleotide (CAG)n repeat expansion in the coding sequence of the huntingtin gene, and an expanded polyglutamine (>37Q) tract in the protein." (PMID 22216210, 2011). "Huntington's Disease (HD) is a neurodegenerative disorder caused by a triplet repeat expansion of the gene Huntingtin (HTT, OMIM 613004)." (PMID 22008211, 2011). "Huntington's disease (HD) is a genetic neurological disorder caused by the expansion of a trinucleotide CAG repeat that encodes the polyglutamine region in the huntingtin protein." (PMID 21931779, 2011). "Expansion of a stretch of polyglutamine in huntingtin (htt), the protein product of the IT15 gene, causes Huntington's disease (HD)." (PMID 20140187, 2010). "Similar to eight other neurodegenerative polyglutamine diseases, Huntington's disease (HD) is associated with a polyglutamine (polyQ) expansion in the huntingtin protein." (PMID 20442863, 2010). "Huntington's disease (HD) is a progressive neurodegenerative disorder caused by a CAG repeat expansion within the huntingtin gene." (PMID 20569486, 2010). "The mutation in Huntington's disease is a polyglutamine expansion near the N-terminus of huntingtin." (PMID 21156064, 2010). "The underlying cause of Huntington’s disease is the inheritance of a copy of the gene encoding huntingtin with an expanded polyglutamine-encoding CAG repeat located within the 5′ end of the coding region." (PMID 20714308, 2010). "Huntington disease (HD) is caused by an expansion of a normal CAG repeat in the gene encoding the protein huntingtin." (PMID 21156064, 2010). "Huntington's disease (HD) is an autosomal dominant neurodegenerative disorder linked to expanded CAG-triplet nucleotide repeats within the huntingtin gene." (PMID 20836877, 2010). "Huntingtin (htt) is a multi-domain protein of 350 kDa that is mutated in Huntington's disease (HD) but whose function is yet to be fully understood." (PMID 20515468, 2010). "Huntington's disease (HD) is a progressive neurodegenerative disorder caused by a glutamine-encoding CAG repeat expansion within the huntingtin gene." (PMID 20569486, 2010). "Huntington’s disease (HD) is a dominantly inherited neurodegenerative disease caused by a CAG repeat expansion in the first exon of the gene Huntingtin (Htt)." (PMID 21037797, 2010). "The proximate cause of neuronal dysfunction and death in Huntington Disease (HD) is the presence of soluble mutant huntingtin (mtHtt) protein or its cleavage products [." (PMID 21278900, 2010). "The N-terminal region of the Huntingtin protein with expanded polyglutamine repeats (either 72 or 103 repeats: HtQ72, HtQ103), which is associated with Huntington's disease, fused to GFP was expressed in a sup35 mutant strain along with NMPM-CSC." (PMID 19470166, 2009). "Huntington's disease is a neurodegenerative disorder characterized by loss of striatal neurons, is caused by an expansion of a polyglutamine tract in the HD protein Huntingtin." (PMID 19698110, 2009).
Huntington disease (continued). "Huntington’s disease is caused by expansion of a polyglutamine tract found in the amino-terminal of the ubiquitously expressed protein huntingtin." (PMID 19451134, 2009). "Aggregates of GFP fused to HtQ103p, the mutated first exon of the Huntingtin protein (HtQ103), whose aggregation is associated with Huntington's disease and enhances de novo formation of [PSI+], fail to enhance the formation of [CHI+PM]." (PMID 19470166, 2009). "Expansion of a polyglutamine repeat at the amino-terminus of huntingtin is the probable cause for Huntington's disease, a lethal progressive autosomal-dominant neurodegenerative disorders characterized by impaired motor performance and severe brain atrophy." (PMID 19203385, 2009). "Huntington's disease is an inherited neurodegenerative disorder due to a mutation in exon 1 of the Huntingtin gene that encodes a stretch of polyglutamine (poly Q) residues close to the N-terminus of the Huntingtin protein." (PMID 20042103, 2009). "For example, reduction of huntingtin aggregates in a model of Huntington's disease through activation of macroautophagy limits neuronal loss and behavioral deficits." (PMID 19754977, 2009). "Huntingtin is a large protein with an estimated molecular mass of 350 kDa, which contains a polyglutamine tract near its N terminus expansion of which causes Huntington's disease." (PMID 19594871, 2009). "For example, Huntington's disease (HD) is caused by a polyglutamine expansion repeat in Huntingtin (Htt) and characterized, in part, by abnormal REST trafficking and transcriptional dysregulation." (PMID 19997604, 2009). "An abnormal polyglutamine (polyQ) expansion in the N-terminal part of the huntingtin protein causes Huntington's disease (HD), a fatal neurodegenerative disorder characterized by the dysfunction and death of striatal and cortical neurons in the brain." (PMID 19860865, 2009). "Huntington's disease (HD) is an inherited neurogenerative disease caused by an abnormal expansion of glutamine repeats in the huntingtin protein." (PMID 19860865, 2009). "Huntington's disease (HD) is a progressive neurodegenerative disorder caused by expansion of an unstable CAG repeat in the coding sequence of the Huntingtin (HTT) gene." (PMID 19997493, 2009). "Huntington's disease (HD) is an autosomal-dominant neurodegenerative disorder which is caused by polyglutamine (polyQ) expansion in the amino-terminus of huntingtin (Htt)." (PMID 18412970, 2008). "Huntington’s disease is an autosomal dominant neurodegenerative disorder caused by the expansion of a polyglutamine repeat tract in the huntingtin protein." (PMID 18840504, 2008). "Huntington's disease is an inherited neurodegenerative disorder that is caused by the expansion of an N-terminal polyQ stretch in the huntingtin protein." (PMID 18005438, 2007). "A critical issue in understanding Huntington's disease (HD) pathogenesis is how the ubiquitously expressed mutant huntingtin (mhtt) with an expanded polyglutamine repeat can cause selective toxicity of striatal and cortical neurons." (PMID 17470275, 2007). "Huntington's disease (HD) is caused by a dominant polyglutamine expansion within the N-terminus of huntingtin protein and results in oxidative stress, energetic insufficiency and striatal degeneration." (PMID 17396163, 2007). "Huntington disease (HD) is caused by expansion of a polyglutamine (polyQ) domain in the protein known as huntingtin (htt), and the disease is characterized by selective neurodegeneration." (PMID 17173700, 2006). "Huntingtin, the HD gene encoded protein mutated by polyglutamine expansion in Huntington's disease, is required in extraembryonic tissues for proper gastrulation, implicating its activities in nutrition or patterning of the developing embryo." (PMID 16109169, 2005).